DUTP1 (deoxyuridine triphosphatase pseudogene 1)
Synonyms: formerly DUTL
Gene: Processed pseudogene on chromosome 3 (125,310,881 to 125,311,350, forward strand). Ensembl gene ENSG00000229048.
Diseases named in the same sentence as DUTP1 in open-access papers:
DUTP1 is named in the same sentence as 1 disease in open-access papers, as found by Europe PMC text mining. Sharing a sentence is not in itself a finding about the gene and the disease. The quoted sentences say what the papers report.
infection (1 paper, 2015). The state of being infected such as from the introduction of a foreign agent such as serum, vaccine, antigenic substance or organism. "As the expression of pseudogene DUTP1 goes from a >1.5-fold decrease at 12 h post-infection to a >8-fold increase at seven days post-infection, its parent gene expression is modulated as well from over-expressed to under-expressed." (PMID 26426037, 2015).